NDRG1 (N-myc downstream regulated 1)
Diseases named in the same sentence as NDRG1 in open-access papers (continued):
Sharing a sentence is not in itself a finding about the gene and the disease.
colon carcinoma (35 papers, 2004 to 2025). "The results of this study showed increases in NDRG1 expression in poorly differentiated colon cancer cells, causing apoptosis." (PMID 27447608, 2016). "Future work will be required to explore how Ndrg1 mechanistically regulates differentiation in BLM colon tumors." (PMID 38893159, 2024). "It has also been reported that NDRG1 can modulate the nuclear translocation of beta‐catenin and hence influence epithelial‐to‐mesenchymal transition in prostate and colon cancer cells." (PMID 40530439, 2024). "NDRG1 expression was first found to be upregulated upon cell differentiation in colon epithelial cells and downregulated in colon cancer." (PMID 36497221, 2022). "In various types of cancers, such as prostate, pancreatic and colon cancers, NDRG1 plays an important role in inhibiting epithelial-mesenchymal transition (EMT), cell migration and angiogenesis." (PMID 34077484, 2021). "NDRG1 suppresses metastasis of tumors in prostate, pancreatic, breast and colon cancers (Kovacevic, Fu & Richardson, 2008)." (PMID 31205821, 2019). "This is in accordance with a previous report, where NDRG1 was found to co-localize with gamma-tubulin in the centrosomes in colon cancer cells." (PMID 31029158, 2019). "The N-myc downstream-regulated gene 1(NDRG1) has been reported as a potential metastasis suppressor by maintaining the localization of E-cadherin and β-catenin in prostate and colon cancer cells." (PMID 29801473, 2018). "N-myc downstream-regulated gene 1 (NDRG1) has been reported as a possible metastasis suppressor by maintaining the localized E-cadherin and β-catenin in prostate and colon cancer cells." (PMID 29801473, 2018). "Overexpression of NDRG1 in colon cancer cells inhibits the nuclear localization of PAK4, increasing the levels of membrane-associated β-catenin and downregulating β-catenin transcriptional activity." (PMID 28430641, 2017). "They found that NDRG1 is downregulated in colon cancer and that NDRG1 overexpression inhibits cell migration in vitro and cancer metastasis in vivo." (PMID 27447861, 2016). "In agreement with these latter studies, NDRG1 has also been demonstrated to promote the membrane expression of β-catenin in breast, prostate and colon cancer cells." (PMID 26431493, 2015). "NDRG1 expression was also found to inhibit cell proliferation in the metastatic colonic cancer cell line, HCT116." (PMID 26431493, 2015). "NDRG1, a 43 kD protein composed of 394 amino acids, was originally identified during the differentiation of colon carcinoma cell lines." (PMID 24269992, 2013). "NDRG1 also induces colon cancer cell differentiation by upregulating the expression of several colonic epithelial cell differentiation markers, namely, alkaline phosphatase, carcinoembryonic antigen and E-cadherin." (PMID 24260043, 2013). "Previous research has also demonstrated that NDRG1 gene reactivation in pancreatic, gastric, and colon cancer cell lines by the pharmacologic reversal of DNA methylation occurred via an indirect mechanism." (PMID 23899187, 2013). "Li and Chen study showed that the silencing of NDRG1 in colon cancer cell lines SW620 and SW480 was due to histone modifications, other than promoter hypermethylation." (PMID 23874837, 2013). "It appears that NDRG1 is a potential metastatic-related cancer suicide gene because when the gene is over-expressed, it induces apoptosis in human colonic cancer cell lines [17 & 18]." (PMID 23555679, 2013).
colon carcinoma (continued). "Recent studies have demonstrated that NDRG1 modulates Wnt-β-catenin signaling pathway with enhanced expression of E-cadherin in human prostate and colon cancer cell." (PMID 22844455, 2012). "On the other hand, NDRG1 is well known to suppress metastasis and cell proliferation by prostate and colon cancer cells." (PMID 22844455, 2012). "Studies addressing the mechanism of Ndrg1 down-regulation in colon cancers will shed more light on the function of Ndrg1 protein and its relation to cancer development." (PMID 15341671, 2004). "With the exception of colon cancer, staining with Ndrg1 antibody distinguished between normal and tumour cells in most cancerous tissues." (PMID 15341671, 2004). "NDRG1 was first recognized as a metastasis suppressor in colon cancer." (PMID 38271137, 2024). "Def was previously reported to increase NDRG1 levels in cervical, prostate, and colon cancer cells." (PMID 39457585, 2024). "This was clearly different from studies using prostate and colon cancer cells where NDRG1 expression caused no significant (p > 0.05) alteration in total β-catenin." (PMID 38815861, 2024). "Notably, this EMT-driving interaction between NDRG1 and E-cadherin in gastric cancer is quite opposite of what was observed in the colon cancer cell line." (PMID 36497221, 2022). "In addition, NDRG1 has often been shown to be downregulated in numerous types of human malignancy, including prostate, breast and colon cancer." (PMID 25777142, 2015). "For the reasons that are unknown, Ndrg1 was expressed at lower levels in colon cancer than it was in normal colon." (PMID 15341671, 2004). "It has been reported that in colon cancer cells, iron chelators antagonize the reduction of E-cadherin expression in response to transforming growth factor-β, and that their effect is dependent on the induction of N-myc downstream-regulated gene 1 (NDRG1) upon iron chelation." (PMID 36009179, 2022). "However, NDRG1 functioned as a metastatic suppressor in prostate and colon cancers." (PMID 21912630, 2011). "Our previous investigations examining the effect of NDRG1 overexpression on WNT signaling in prostate and colon cancer cells demonstrated a distinctly different mechanism to that reported herein." (PMID 38815861, 2024). "Following the combined decitabine/PBA treatment of colon cancer cells, we observed a highly significant sixfold induced expression of XIST and a three- and twofold induction, respectively, of its target genes NDRG1 and SEMA6A." (PMID 37208732, 2023). "Taken together, CLDN2‐mediated NDRG1 suppression modulates the expression of downstream EMT markers and CDKI genes to facilitate colon cancer progression." (PMID 34965023, 2021). "N-myc downstream-regulated gene 1 (NDRG1), a potent metastasis suppressor, inhibits EMT in prostate and colon cancer cells." (PMID 28430641, 2017). "NDRG1 is a potent metastatic suppressor that has been shown to restrain TGF-ß-induced EMT in prostate and colon cancer cells, while its reduction induces EMT." (PMID 27894074, 2017). "They demonstrated a correlation between the increased histone H3S10p and silencing of the NDRG1 gene in colon cancer cell line SW620, suggesting a potential mechanism of NDRG1 repression during colon cancer metastasis." (PMID 23874544, 2013).
colon carcinoma (continued). "As a differentiation‐related gene, previous studies have found NDRG1 expression in colonic epithelium and well‐differentiated colon cancer cells but not in metastatic colon cancer tissues and cell lines." (PMID 40151835, 2025). "Moreover, we demonstrated XIST and its targets NDRG1 and SEMA6A to be significantly repressed in clinical samples (Fig. 5B2) and provided evidence for hypermethylation of NDRG1 and SEMA6A in colon cancer clinical samples (Fig. 5B3)." (PMID 37208732, 2023). "Their experiment carried out in colon carcinoma cells (SW480) supports our results, indicating that the high stability of Ndrg1 protein is not cell specific." (PMID 15341671, 2004).
gastric cancer (29 papers, 2012 to 2025). A primary or metastatic malignant neoplasm involving the stomach. "NDRG1 expression is also associated with poor prognosis and malignant progression in gastric cancer." (PMID 36497221, 2022). "Conversely, NDRG1 can stimulate tumor growth, spread, angiogenesis, and poor prognosis in other malignancies, such as lung cancer, bladder cancer, gastric cancer, and invasive breast cancer." (PMID 37858101, 2023). "The RNA-seq data of gastric cancer from the TCGA database demonstrated that the mRNA expression of NDRG1 was downregulated in STAD tumor tissues and was significantly negatively correlated with invasion depth." (PMID 36979962, 2023). "NDRG1 was found to be significantly upregulated in the highly metastatic gastric cancer cell lines, as compared to the parental cells with low metastatic potential." (PMID 36497221, 2022). "In gastric cancer, NDRG1 nuclear localization is frequently found in the region of cancerous invasion and is correlated with lymph node metastasis." (PMID 35563887, 2022). "Although NDRG1 function is predominantly reported as anti-oncogenic and anti-metastatic, studies also show it to be pro-oncogenic in different cancers such as gastric cancer and HCC." (PMID 36497221, 2022). "NDRG1, a downstream regulatory gene of N‐myc, inhibits metastasis, and recurrence of tumors such as gastric cancer." (PMID 34258887, 2021). "In our dbEMT, NDRG1 was recorded as promoting the malignant progression of gastric cancer through EMT." (PMID 27029057, 2016). "The anti-metastatic function of NDRG1 as a metastasis suppressor protein has been identified in multiple cancers including breast, colon, prostate, and gastric cancers." (PMID 26692161, 2015). "This NDRG1 mediated regulation of E-cadherin and/or vimentin expression affected epithelial mesenchymal transition of gastric cancer cells." (PMID 22844455, 2012). "NDRG1 knockdown in gastric cancer cell showed suppressed invasion of cancer cells into surround tissues, suppressed metastasis to the peritoneum and decreased ascites accumulation in mice with significantly improved survival rates." (PMID 22844455, 2012). "Consistent with this study, we observed that high NDRG1 expression was significantly correlated with tumor angiogenesis and malignant progression together with poor prognosis in gastric cancer." (PMID 22844455, 2012). "This is the first study to demonstrate that NDRG1 plays its pivotal role in the malignant progression of gastric cancer through epithelial mesenchymal transition." (PMID 22844455, 2012). "In our present study, we investigated the metastatic potential of gastric cancer cells by its correlation with EMT-based role of NDRG1." (PMID 22844455, 2012). "Further study is required to understand which regulatory mechanism is specifically responsible for NDRG1 driven promotion of malignant progression by gastric cancer cells." (PMID 22844455, 2012). "Our recent study demonstrated that higher expression of N-myc downregulated gene 1 (NDRG1) is closely correlated with poor prognosis in gastric cancer patients." (PMID 22844455, 2012). "By gene expression microarray analysis expression of NDRG1 showed the higher increase among a total of 3691 up-regulated genes in a highly metastatic gastric cancer cell line (58As1) than their parental low metastatic counterpart (HSC-58)." (PMID 22844455, 2012). "Of various regulatory factors that transcriptionally control E-cadherin, expression of Snail was specifically modulated by NDRG1 in gastric cancer cell lines used in this study." (PMID 22844455, 2012). "Of various transcription factors that suppress expression of E-cadherin including Snail, Slug, Twist, TCF4 and SIP1, expression of Snail was specifically modulated by NDRG1 in gastric cancer cells." (PMID 22844455, 2012).
gastric cancer (continued). "We focused on one gene named N-myc downstream regulated gene 1 (NDRG1) because it was found to be markedly upregulated in the highly metastatic gastric cancer cell lines compared to their counterpart cells." (PMID 22844455, 2012). "Indeed, reducing NDRG1 levels in gastric cancer cells led to increased E-cadherin expression and decreased vimentin expression, indicating a link between high NDRG1 levels and the metastatic potential of gastric cancer cells." (PMID 39199357, 2024). "Nuclear NDRG1 has previously been shown to be associated with poor survival outcomes in gastric cancer and has not been explored in BC or BrM." (PMID 40530439, 2024). "However, the opposite results were reported in gastric carcinoma where NDRG1 was suggested to be a tumor suppressor protein through inhibition of multiple oncogenic signal pathways." (PMID 38561462, 2024). "On the contrary, NDRG1 can suppress VM formation in gastric carcinoma through inhibition of EMT." (PMID 38561462, 2024). "Expression of NDRG1 has been found to be down-regulated in gastric cancer samples." (PMID 37249826, 2023). "Indeed, knocking down NDRG1 in gastric cancer cells increased E-cadherin expression and suppressed the expression of vimentin; linking the typically high NDRG1 levels to the metastatic potential of gastric cancer cells." (PMID 36497221, 2022). "In addition, our team previously reported that the level of the phosphorylated NDRG1 protein (NDRG1-pT346) is significantly associated with EGFR, EGFR-pY1068, and EGFR-pY1173 protein expression in gastric cancer." (PMID 34385595, 2021). "Recent studies also showed that NDRG1 could inhibit proliferation of gastric cancer, oral squamous cell carcinoma (OSCC) and hepatic tumors and it was associated with good patient survival." (PMID 31831018, 2019). "Recently, it has been shown that promoter methylation of the NDRG1 gene was associated with reduced NDRG1 expression but not with histone modification in gastric cancer cells and tissue samples." (PMID 26692161, 2015). "Our recent study has also reported that human gastric cancer cells overexpressing NDRG1 induces enhanced expression of IL-1α through activation of JNK and AP-1 (Jun/Fos), resulted in promoted expression of angiogenesis-related factors and tumor angiogenesis accompanied by macrophage infiltration." (PMID 24924428, 2014). "NDRG1 knockdown resulted in relatively higher E-cadherin expression in As1/Sic50 tumors than in As1/Mock3 tumors, suggesting that NDRG1 may specifically control the EMT possibly through the transcription factor Snail by gastric cancer cells." (PMID 22844455, 2012). "We have previously reported that NDRG1 is closely correlated with tumor angiogenesis and poor survival in patients with gastric cancer, suggesting that NDRG1 is a predictive biomarker for malignant progression of gastric cancer." (PMID 22844455, 2012). "In conclusion, NDRG1 knockdown induced the upregulation of E-cadherin and downregulation of vimentin and Snail, and suppressed the invasion, metastasis and accumulation of ascites by the highly metastatic gastric cancer cells." (PMID 22844455, 2012). "In this study, we asked whether NDRG1 has pivotal roles in malignant progression including metastasis of gastric cancer cells." (PMID 22844455, 2012). "This molecular mechanism ultimately upregulates NDRG1 expression and enhances migratory capacity in gastric cancer(GC) cells." (PMID 40151835, 2025). "Mircetic and collaborators demonstrated that the histone lysine demethylase-1A (KDM1A) regulates the expression of NDRG1 in a gastric cancer (GC) organoid model through histone demethylation." (PMID 40332138, 2025). "Another study mentioned that MAOA can interact with NDRG1, inhibiting downstream PI3K/AKT/mTOR pathway activity, thereby attenuating the Warburg effect in gastric cancer cells and ultimately suppressing tumor cell proliferation and malignant behavior." (PMID 39010072, 2024).
gastric cancer (continued). "We also assessed the mRNA and protein levels of NDRG1 and DNMTs in one immortalized normal gastric cell line, GES1 and two gastric cancer cell lines, SGC7901 and MKN45 by real-time PCR and western blot." (PMID 34616614, 2021). "NDRG1, in its close context with EMT-related genes, might participate in the acquisition of a high metastatic potential by progressive gastric cancer cells." (PMID 22844455, 2012). "However, levels of NDRG1 and DNMT1 have not been associated with prognosis of gastric cancer." (PMID 37249826, 2023). "In the present study, NDRG1 knockdown resulted in the suppression of metastasis by highly metastatic gastric cancer cells, suggesting that NDRG1 may be a metastasis promoter gene rather than a metastasis suppressor gene in gastric cancer." (PMID 22844455, 2012).